SMAD3 (SMAD family member 3)
Diseases named in the same sentence as SMAD3 in open-access papers (continued):
Sharing a sentence is not in itself a finding about the gene and the disease.
renal fibrosis (continued). "Smad3 knock-out mice or Smad3 inhibitors attenuate renal fibrosis and inflammation in diabetic mice, suggesting that the TGF-β1/Smad3 signaling pathway contributes to renal fibrosis and inflammation in diabetic nephropathy." (PMID 34775979, 2021). "In addition, as ERK1/2 can interact with Smad3 to TGF-β1-stimulated multiple biological functions including renal fibrosis, I-BET151 may also inhibit renal fibrosis through interfering with ERK1/2-mediated regulation of Smad3 and other profibrotic machinery downstream of TGFβ receptors." (PMID 33664670, 2021). "Several previous publications have highlighted that SKI retarded renal fibrosis by inhibiting levels of interleukin-6, interleukin-1β, and TNF-α and modulating TGF-β1/Smad3 and JAK2/STAT3 signaling pathways." (PMID 35002735, 2021). "Thus, we hypothesized that RDV attenuated renal fibrosis through Smad3." (PMID 34276356, 2021). "Concerning the anti-fibrotic effect of genistein, a study in a rat diabetic model revealed that genistein treatment attenuated renal fibrosis as shown by lower levels of TGF-β1, p-Smad3, and collagen IV compared to diabetic untreated rats." (PMID 35052518, 2021). "We further found that ZQTF ameliorated hyperuricemic kidney injury by inhibiting renal fibrosis, enhancing renal fatty acid metabolism via downregulating the expression of the TGF-β1/Smad3 signaling pathway." (PMID 34938805, 2021). "Using rat pTECs, they demonstrated that TGF-β promoted renal fibrosis by inducing miR-21 which in turn targets Smad7 and PTEN, the negative regulators of Smad3 and PI3K, respectively." (PMID 33364960, 2020). "In summary, our results indicate that BAI, and particularly the kidney-targeted BAI-LZM conjugate, produced inhibition of renal fibrosis and inflammation via the NF-κB, TGF-β1/Smad3 and IGF-1/p38 MAPK signaling pathways." (PMID 32398108, 2020). "MSCs transfusion effectively suppressed renal fibrosis in experimental models by inhibiting both the pro-inflammatory and pro-fibrotic signaling pathways, including TGF-β1/Smad3, TLR4/NK-κB, and ERK." (PMID 32512831, 2020). "Smad2 and Smad3, two major downstream mediators of transforming growth factor-β1 (TGF-β1), play a dominant role in kidney dysfunction and renal fibrosis." (PMID 32957963, 2020). "During the early stages of renal fibrosis, continuous inflammatory response of renal tubular cells and immune cells promotes TGF‐β/Smad pathway activation and overexpressed Smad2 and Smad3 further activate the NF‐kB pathway in turn." (PMID 32253812, 2020). "In renal fibrosis, for example, activated SMAD3 promotes PAI-1 expression in human renal tubular epithelial cells, confirming SMAD3 as a pro-fibrotic mediator in epithelial cells." (PMID 33322749, 2020). "We consider TGF-β1/Smad3-mediated EMT transcription factors as the key point for preventative or therapeutic 3-MA administration to inhibit EMT, thus blocking renal fibrosis." (PMID 32555189, 2020). "An earlier report showed that active vitamin D3 inhibited renal fibrosis through promoting direct interaction VDR and Smad3." (PMID 31775746, 2019). "Because TGF‐β1/Smad3 signalling is the critical pathway of renal fibrosis, we first examined the effect of petA on the activation of TGF‐β1/Smad3 signalling in the UUO model." (PMID 31211499, 2019). "RSV treatment also decreased the phosphorylation of Smad3 and reduced SIRT1 binding to Smad3 and Smad4, an important interaction involved in the progression of renal fibrosis." (PMID 31319485, 2019).
renal fibrosis (continued). "In vitro experiments suggest that these miRNA combinations promote renal fibrosis by increasing profibrotic molecules through SP1 and Smad3/TGFβ pathways." (PMID 31349698, 2019). "In the current study, we have demonstrated that expression of RUNX1, but not RUNX2 or RUNX3, was induced in the process of TGF-β-induced EMT in a SMAD3-dependent manner and in UUO-induced renal fibrosis in vivo." (PMID 29759484, 2018). "Here, we demonstrate that RUNX1 is overexpressed in the processes of TGF-β-induced partial EMT and renal fibrosis and that the expression level of RUNX1 is SMAD3-dependent." (PMID 29759484, 2018). "In renal fibrosis in rats, TGF-β-induced miR-21 up-regulation was mediated by Smad3 or sphingosine kinase/sphingosine-1-phosphate (SphK/S1P) signalling." (PMID 29892003, 2018). "As a participant in the process of fibrosis through activation of Smad2 and Smad3 phosphorylation, TGF-β/Smad signalling is considered to be the key regulator in renal fibrosis." (PMID 30134806, 2018). "In conclusion, our study provides the first direct evidence that celastrol significantly alleviated renal fibrosis, by contributing to the upregulation of CB2R expression through inhibiting Smad3 signaling pathway activation." (PMID 29789558, 2018). "Dysregulation of Smad7 promotes renal fibrosis and conversely Smad7 treatment substantially attenuating progressive kidney diseases via inactivating TGF-β/Smad3 signaling." (PMID 30524310, 2018). "We also investigated the expression of Smad3, the downstream target of TGF-β1, to confirm the involvement of TGF-β1 in the BZM-mediated improvement of renal fibrosis." (PMID 29026167, 2017). "In a recent example, the hydroxylated pentapeptide VHL-recognition motif was used to target SMAD family member 3 (SMAD3), a key signalling protein in renal fibrosis, for degradation." (PMID 28298557, 2017). "Blockade of the CRP signaling with an anti-CD32b antibody or Smad3 signaling with a specific inhibitor (SIS3) was able to inhibit mTOR signaling, thereby attenuating renal fibrosis including mesangial expansion under high CRP conditions in vivo and in vitro." (PMID 27221338, 2016). "Although the TGF-β signaling pathway is mediated by Smad2 and Smad3, Smad2 protects against TGF-beta/Smad3-mediated renal fibrosis." (PMID 28100935, 2016). "Our study demonstrated that Sirt1 inhibits renal fibrosis at least partially by inhibiting AT1R and NF-κB expression, and previous studies also supported that Sirt1 inhibits renal fibrosis by inducing COX2, deacetylating Smad3 and STAT3." (PMID 27659793, 2016). "In the context of renal fibrosis, TGF-β1 acts by stimulating Smad3 to mediate fibrosis, which is negatively regulated by Smad7." (PMID 25883225, 2015). "Thus, the combination of AA and NG produces an additive effect on inhibition of renal fibrosis by inhibiting Smad3 while upregulating Smad7 and may represent as a novel and effective therapy for chronic kidney disease including diabetic and hypertensive nephropathy." (PMID 26474462, 2015). "In patients with renal fibrosis and IgA nephropathy, the urinary miR-93 level correlated with the degree of glomerular scarring and was regulated by the TGF-β1/SMAD3 pathway." (PMID 25884636, 2015). "In addition, inhibition of TGF-β/Smad3-mediated renal fibrosis by overexpressing renal Smad7 in the established chronic AAN further supported the inhibitory role of Smad7 in progressive chronic AAN and may also well explain the therapeutic effect of Smad7 on chronic AAN." (PMID 25883225, 2015). "We have previously reported that miR-29b is a downstream target gene of Smad3 and it is negatively regulated by TGF-β/Smad signaling in renal fibrosis." (PMID 25356754, 2015). "It has been observed that UUO induces an increase in Smad2 and Smad3 phosphorylation, and the contribution of TGF-β/Smad2/3 pathway in renal fibrosis have been extensively studied." (PMID 25313562, 2014).
renal fibrosis (continued). "In our previous study, intrarenal infusion of clusterin reduced the level of renal fibrosis and decreased PAI-1, matrix protein expression, and TGF-β/Smad3 activity in UUO mice, indicating that clusterin plays a protective role in renal fibrosis." (PMID 25148511, 2014). "Previous reports have demonstrated that Smad3, a key signaling intermediate downstream of the TGF‐β receptors, is a key molecule mediating TGF‐β1‐induced renal fibrosis in the UUO model." (PMID 24973329, 2014). "It is now clear that microRNA-21 is regulated by TGF-β/Smad3 and acts as a downstream mediator of TGF-β/Smad3-driven renal fibrosis." (PMID 24646636, 2014). "GS-HCl administration significantly reduced elevated Smad3 phosphorylation level in the obstructed kidneys, implying its ability to attenuate TGF-β signaling in renal fibrosis in vivo." (PMID 24072041, 2013). "Conditional gene deletion of Smad2 exacerbates renal fibrosis in the unilateral ureteric obstruction (UUO) model, whereas Smad3 gene deletion (Smad3-/-) mice is protective against fibrosis." (PMID 24391884, 2013). "The results of the study showed that exogenous supplementation with EC and ECF successfully reduced creatinine and urea nitrogen levels; down-regulated the expression levels of TGF-β1, α-SMA, Smad3, and phospho-Smad3 in the TGF-β1/Smad signaling pathway; and ameliorated renal fibrosis." (PMID 40430564, 2025). "MMT plays a crucial role in renal fibrosis through various mechanisms, including the transforming growth factor-β 1 (TGF-β 1)/Smad3 signaling pathway and natural killer T cell (NKT)/IL-4 signaling pathway, as well as the adiponectin/APK pathway and ALD/MR/TGF-β 1 signaling pathway." (PMID 40332144, 2025). "Notably, the balance between pro-fibrotic Smad3 and anti-fibrotic Smad7 is crucial to TGF-β1’s role in the progression of renal fibrosis." (PMID 40092979, 2025). "It has also been reported to attenuate renal fibrosis through reductions in the expression of fibronectin and Notch1 and the inhibition of the type II TGFβ receptor/Smad3 pathway in human embryonic kidney cells." (PMID 41020857, 2025). "Significantly, Smad3 knockout models reduced CD206+ MMT cells and renal fibrosis and suggested that selective targeting of this pathway may have therapeutic value." (PMID 41463309, 2025). "Thus, in this study, we aimed to uncover the mechanistic link between TGF-β/Smad3 signaling and GPX4-dependent ferroptosis in the development of renal fibrosis." (PMID 41079940, 2025). "Researchers have developed and validated AANG—a botanical formulation comprising asiatic acid (a Smad7 activator) and naringenin (a Smad3 inhibitor) that attenuates renal fibrosis and inflammation in DKD through modulation of the TGF-β/Smad3/Smad7 signaling pathway." (PMID 40861214, 2025). "Mice lacking Smad3 (Smad3ex8/ex8) are protected against renal fibrosis following ureteral obstructive nephropathy." (PMID 40141345, 2025). "Our study indicated that OA might exert anti-renal fibrosis effects through the activation of Sirt1 and the suppression of the TGF-β/Smad3 signaling pathway." (PMID 39687299, 2024). "Importantly, ZLD2218 blocked UUO-induced activation of the TGF-β/Smad3 signaling pathway and suppressed α-SMA, COL I, COL IV and FN expression, significantly attenuating renal fibrosis and renal injury." (PMID 39215370, 2024). "Consistent with previous studies that found that Smad2,Smad3,Smad4 and Smad7 might be involved in TGF-β1-mediated renal fibrosis, our study observed alterations in the phosphorylation activation of Smad2,Smad3,Smad4 and Smad7 in TGF-β1 treated HK-2 cells." (PMID 38195664, 2024).
renal fibrosis (continued). "We found that anti-Smad3 treatment on pre-diabetic db/db mice largely attenuated both T2D and T2DN by markedly reducing blood glucose levels, and inhibiting the elevated serum creatinine, microalbuminuria, and renal fibrosis and inflammation." (PMID 38164169, 2024). "Moreover, the administration of EPE to db/db mice increased the expression levels of p- PKCα/t-PKCα but decreased the expression levels of VEGF and renal fibrosis biomarkers (TGF-β1, collagen IV, p-Smad2, p-Smad3, and Smad4), as shown by Western blot analyses." (PMID 38928391, 2024). "In the unilateral ureteral obstruction (UUO) mouse model, the absence of Smad3 significantly reduces renal fibrosis." (PMID 39431155, 2024). "In the process of renal fibrosis, miR-192 is regulated by TGF-β1 via Smad3." (PMID 39444490, 2024). "In a rat nephrectomy model, overexpression of Smad7 blocked TGF-β/Smad signaling, and thereby inhibited miR-192 expression and renal fibrosis, suggesting that miR-192 may be an important downstream of the TGF-β/Smad3 signaling pathway." (PMID 37170506, 2023). "PA reduced the BP, RAAS, inflammation and cytokines, promoted the urine, and relieved renal pathological injury and collagen deposition, repaired renal fibrosis, decreased the expression of NADPH Oxidase 4 (NOX4), transforming growth factor-β (TGF-β), SMAD3 and MAPK signaling pathway in SHR rats." (PMID 37353787, 2023). "Isolated from Resina Toxicodendron, GQ5 is a small compound that inhibits SMAD3 and downregulates renal fibrosis without any obvious adverse effect." (PMID 37762322, 2023). "Notably, Smad3 inhibits ECM breakdown by directly binding to the promoter region of collagens to activate their production, promoting renal fibrosis." (PMID 36835428, 2023). "Smad3 knockout significantly alleviates renal fibrosis in models of obstructive nephropathy, DKD, and other diseases, and TGF-β1 can inhibit the activity of antioxidant enzymes to mediate the occurrence of Smad3-dependent renal fibrosis." (PMID 35908070, 2022). "Smad3 can directly activate the tyrosine kinase Src and trigger collagen production, which inhibits the degradation of ECM, renal interstitial fibroblast activation, and renal fibrosis." (PMID 35990655, 2022). "LSD1 deficiency leads to alleviate STZ-induced renal injury and overexpression of LSD1 induces renal fibrosis via decreasing SIRT3 expression and activating TGF-β1/Smad3 pathway, which provides a reasonable strategy for developing novel drugs targeting LDS1 to block renal fibrosis." (PMID 34983623, 2022). "Moreover, has-mir-136-5p can improve renal fibrosis by targeting SYK and inhibition of TGF-β1/Smad3 signaling pathway." (PMID 35755170, 2022). "Fortunately, we have proved that LSD1 could activate TGF-β1/Smad3 pathway, providing an explanation why LSD1 induced renal fibrosis." (PMID 34983623, 2022). "In this study, we demonstrate that pharmacological and genetic inhibition of HDAC4 attenuates renal fibrosis and suppresses the molecular mechanisms leading to renal fibrosis, including the pEMT, fibroblast activation, and activation of the TGF-β1/Smad3, STAT3, and ERK1/2 signaling pathways." (PMID 35847036, 2022). "It is now recognized that Smad3 but not Smad2 is the primary transcriptional factor mediating renal fibrosis in various types of CKD." (PMID 36091385, 2022). "Interestingly, in an unexpected finding, resveratrol interacted with both SMAD3 and SMAD4 simultaneously to prevent the formation of the SMAD3/4 complex via SIRT1, inhibiting SMAD3 phosphorylation and renal fibrosis." (PMID 35277012, 2022). "In conclusion, this experimental study shows that β-elemene reduces renal fibrosis by targeting JAK2/STAT3, Smad3, and Myd88 signaling factors and may serve as a potent inhibitor of STAT3 and Smad3 in the future." (PMID 35628363, 2022). "During renal fibrosis, TGF-β1 mainly activates downstream Smad3 signaling." (PMID 36105187, 2022).
renal fibrosis (continued). "Given the roles of TGF-β1/Smad3 pathway and SIRT3 in renal fibrosis, we hypothesized that LSD1 might play a vital role in DN-induced renal fibrosis through regulating SIRT3." (PMID 34983623, 2022). "The present effort has documented that fasudil downregulates TGF-β1 and p-Smad3 expression levels and inhibits α-SMA induction during CA-AKI, which may profoundly reduce renal fibrosis over relatively long periods." (PMID 35784704, 2022). "Thus, TGF-β-induced tubular miR-192 expression is Smad3-dependent because knockdown of Smad3 can block TGF-β1-induced tubular miR-192 expression and renal fibrosis." (PMID 35541902, 2022). "In contrast, CRP Tg mice lacking Smad3 (CRP Tg/Smad3 KO) were protected from CRP-exacerbated renal fibrosis by inhibiting expressions of collagen I, fibronectin, and α-SMA mRNA and protein." (PMID 34671208, 2021). "BHD could attenuate renal fibrosis and inflammation in STZ-induced diabetic kidneys via inhibiting TGF-β1/Smad3 and NF-κB signaling while suppressing the Arkadia and restoring renal Smad7." (PMID 34775979, 2021). "Moreover, lncRNA MEG8 downregulates the expression of Smad2, Smad3, Colla1 and α-SMA, and leads to the formation of myofibroblasts, which ultimately alleviates the progression of renal fibrosis." (PMID 34477472, 2021). "Since CRP mediates renal fibrosis by stimulating TGF-β1 expression, we hypothesized that CRP-induced TGF-β1 expression may be Smad3 dependent." (PMID 34671208, 2021). "Here, we tested a hypothesis that CRP may promote renal fibrosis and inflammation via a TGF-β/Smad3-dependent mechanism." (PMID 34671208, 2021). "In addition, miR‐136 has been shown to improve renal fibrosis in diabetic rats through down‐regulation of tyrosine kinase SYK and TGF‐β1/Smad3 pathway." (PMID 33942982, 2021). "While nintedanib treatment in our study significantly reduced renal fibrosis in Pkd1RC/RC mice, it did not affect activity of SMAD3, an important component of TGFβ signaling." (PMID 34650051, 2021). "The constructs they created that specifically lacked serine 204 also reduced Smad3 α2(I) collagen promoter activity, further indicating a key role for it in the development of renal fibrosis." (PMID 34003249, 2021). "Encouragingly, a Smad3 specific inhibitor SIS3 and a natural compound isolated from Poria cocos Poricoic acid effectively suppressed renal fibrosis development in experimental models of diabetic nephropathy, obstructive nephropathy, and ischemia-reperfusion injury in vivo." (PMID 33718407, 2021). "Angiotensin‐converting enzyme inhibitors can effectively protect against renal fibrosis and reduce the incidence of CKD by inhibiting DPP‐4, phosphorylation of Smad3 and increasing miR‐29s expression in the kidneys of DM‐induced mice and in human endothelial cells." (PMID 33529442, 2021). "We reported that Fyn deficiency inhibits renal fibrosis by reducing the expression of phospho-STAT3, but not of Smad3." (PMID 32120837, 2020). "Further investigation revealed that Arid2-IR stimulates the NF-κB-dependent renal inflammatory pathways without effect on TGF-β1/Smad3-mediated renal fibrosis in vitro and in vivo." (PMID 32295041, 2020). "While Smad2 deletion in mouse tubular epithelial cells accelerated renal fibrosis by enhancing SMAD3 activation, conditional deletion of Smad4 in mouse tubular epithelial cells significantly reduced fibrosis without affecting SMAD3 activation." (PMID 33322749, 2020). "This research offers valuable insights into the brake nature of GAS5 in renal fibrosis; however, whether JNK and TGF-β/Smad3 signaling are independent requires future studies." (PMID 32752143, 2020). "In conclusion, this study has shown that nodakenin can significantly inhibit UUO‐induced renal fibrosis in mice and TGF‐β1‐treated renal epithelial cells by regulating NF‐κB and Smad3 induced Snail1 expression, subsequently improving the inflammation and fibrogenesis in the obstructive kidney." (PMID 32696548, 2020).